CRP (C-reactive protein)
Diseases named in the same sentence as CRP in open-access papers (continued):
Sharing a sentence is not in itself a finding about the gene and the disease.
meningitis (continued). "However, previous studies that showed CRP as a good guide excluded high-risk infants with central lines, mechanical ventilation, postsurgery, meningitis, birth asphyxia, and those with positive initial CRP." (PMID 22164179, 2011). "Meningitis associated clinical characteristics and laboratory parameters were compared by using univariate analysis, significant differences(P < 0.05) were demonstrated in peripheral WBC count, CRP, PCT, CSF WBC count, CSF ANC, CSF glucose, CSF protein and positive Gram stain between the BM and AM." (PMID 36759812, 2023). "Patients < 12 months (OR: 16.04) and with septic shock (OR: 23.4), vomit (OR: 13.33), convulsion (OR: 15.86), C-reactive protein (CRP) ≥ 40 g/L (OR: 5.56), and a higher level of procalcitonin (PCT) (OR: 1.05) on admission were statistically associated to an increased risk of developing meningitis." (PMID 36040531, 2022). "For example, in meningitis, the median day 1 PCT was 3.87 ng/mL (IQR: 2.54-5.24), and the median CRP was 111.96 mg/L (IQR: 75.82-151.30)." (PMID 40546523, 2025). "Through multivariate Logisitic regression analysis, it was determined that CRP, TNF-a, IL-6, PCT, and IL-1 were reliable predictors of the efficacy of Dexamethasone treatment in children with refractory purulent meningitis." (PMID 39139150, 2024). "Predictive efficacy of CRP, TNF-α, IL-6, PCT and IL-1β in children with refractory purulent meningitis treated with dexamethasone." (PMID 39139150, 2024). "Meanwhile, these factors were also elevatedin the control group compared to the healthygroup, which aligns with previous research and indicatesa clear elevation of that CRP, TNF-α, IL-6, PCT,and IL-1β in children with refractory purulent meningitis." (PMID 39139150, 2024). "In fact, PCT has shown a better performance than traditional markers (CRP, CSF ANC, CSF protein, etc.)to identify invasive bacterial infection, specifically for meningitis." (PMID 36759812, 2023). "In their study, it was shown that C-reactive protein (CRP) and procalcitonin were significantly lower than that of meningitis after ES, with the clinical findings being similar." (PMID 37900516, 2023). "Regarding laboratory investigations on admission, we found that the C-reactive protein concentration (median (IQR)) was 36 mg/L (15.0–165.9 mg/L) in CAP, 47 mg/L (20.0–193.0) in meningitis, and 24 (13.05–38.90) in other diagnoses." (PMID 34641809, 2021). "In 151 adults with confirmed meningitis admitted to our ED, we confirmed that PCT was a high predictor of BM (AUC of 0.99) compared to 0.75 for CRP ( p < 0.05), with a best threshold value of 2.13 ng/mL." (PMID 19578505, 2008). "Therefore, CRP,TNF-α, IL-6, PCT, and IL-1β can be applied as one ofthe crucial indicators to evaluate the curative effect ofrefractory purulent meningitis in children." (PMID 39139150, 2024). "Moreover, serum and CSF HBP levels were higher in children with purulent meningitis than those with viral meningitis compared to other infection biomarkers, including PCT, CRP, and tumor necrosis factor (TNF)-α." (PMID 38297213, 2024). "Also, the analysis of laboratory findings showed that the levels of C-reactive protein (CRP) ≥ 40 g/L (P = 0.012) and evaluated procalcitonin (PCT) (P < 0.001) were more common among the patients with meningitis." (PMID 36040531, 2022). "As no baby with CRP <10mg/L was subsequently re-admitted with a positive CSF, it is reasonable to assume they are likely not to have had meningitis." (PMID 30509228, 2018). "Reflecting the likely different response to meningitis in term babies, several one-centre reports as well as one review question, suggest no asymptomatic term baby had meningitis regardless of CRP level." (PMID 30509228, 2018). "In non-meningitis studies, statistically significant findings for CRP levels were reported in bacterial versus non-bacterial infections, but the related sensitivities and specificities ranged widely across studies." (PMID 27486746, 2016).
meningitis (continued). "It is reported that plasma inflammatory markers such as peripheral blood leukocyte count and CRP can be very useful in discriminating between bacterial and nonbacterial meningitis." (PMID 24803939, 2014). "Notably, CRP andIL-1β demonstrated superior predictive performance,suggesting that CRP, TNF-α, IL-6, PCT, and IL-1β canserve as effective indicators for evaluating efficacy ofdexamethasone treatment in children with refractorypurulent meningitis." (PMID 39139150, 2024). "C-reactive protein is an acute phase protein synthesized in the liver upon activation of the immune system with widespread clinical use, but while its increase is sensitive for bacterial infections and meningitis, it is by far not specific." (PMID 37046531, 2023). "In the current study, meningitis was defined as positive CSF findings with increased levels of leukocytes and suspected infection either due to further lab findings such as elevated white blood cells (WBC) and/or C-reactive protein (CRP) and/or clinical findings." (PMID 32020298, 2020). "CRP in neonates with meningitis is reported to be twice more than those without meningitis." (PMID 32494342, 2020). "For this purpose, CRP and PCT have been evaluated as early meningitis markers, being sensitive, but not specific enough." (PMID 32532024, 2020).
ischemia (78 papers, 2010 to 2025). A hypoperfusion of the BLOOD through an organ or tissue caused by a PATHOLOGIC CONSTRICTION or obstruction of its BLOOD VESSELS, or an absence of BLOOD CIRCULATION. "The association between fQRS and elevated CRP levels is pathophysiological plausible, given the well-established role of CRP as a marker of inflammation and myocardial injury in ischemia–reperfusion settings." (PMID 41303859, 2025). "Elevated inflammatory markers such as ERS, CRP, as well as the presence of antineuronal antibodies, are associated with ischemia." (PMID 40416235, 2025). "Elevated CRP levels reflect activation of the IL-1/IL-6 axis and are strongly linked to plaque vulnerability, myocardial necrosis, and recurrent ischemia." (PMID 41226718, 2025). "We investigated the association of serum CRP levels with the presence and extent of ischemia detected after stress-induced MPI SPECT, performed for diagnostic or prognostic reasons." (PMID 38398769, 2024). "CRP was implicated in renal fibrosis and renal ischemia-reperfusion injury, and its increase was significantly related to the occurrence and mortality of AKI." (PMID 34141715, 2021). "Because increased levels of CRP have been associated with arterial-wall inflammation, statins can prevent ischemia by both inhibiting deposition of lipids and decreasing inflammation." (PMID 20920225, 2010). "Subclinical inflammation, as indicated by plasma CRP levels, was associated not only with the presence of coronary atherosclerosis but also with the severity of coronary plaque burden and the clinical manifestation of ischemia." (PMID 38667035, 2024). "IR may increase the release of inflammatory factors such as C-reactive protein and tumor necrosis factor, leading to the adhesion and aggregation of leukocytes, which can cause retinal capillary obstruction and finally local ischemia." (PMID 38130393, 2023). "The CRP is thought to be associated with the “vulnerable patient”, a new concept that is comprised of vulnerable plaque, vulnerable myocardium (prone to ischemia), and vulnerable blood (prone to thrombosis)." (PMID 26406989, 2015). "Additionally, we found that patients with increased CRP have higher risk of MI (OR: 1.52, 95% CI: 1.06–2.18, p = 0.023), suggesting that greater inflammatory burden is correlated with myocardial injury and ischemia." (PMID 39012400, 2024). "In autoimmune patients, only ESR/CRP, bleeding, and ischemia were elevated in the pre-menopausal group." (PMID 41001471, 2025). "The authors concluded from multivariate logistic regressions that in patients with critical ischemia, elevated CRP values are an independent determinant of MALEs and MACEs after revascularization." (PMID 38672153, 2024). "The study shows that the increase of hs-CRP can reflect the degree of vascular injury during ischemia-reperfusion, which provides a certain direction for clinical diagnosis and treatment." (PMID 39465843, 2024). "CRP, an acute-phase inflammatory marker synthesized primarily by the liver under conditions such as infection, trauma, and ischemia, increases in response to proinflammatory cytokines, particularly interleukin-6." (PMID 39685802, 2024). "Applying tourniquets during TKA has been shown to increase the levels of the inflammatory factors CRP and IL-6, probably as a result of ischemia and damage to soft tissue." (PMID 37119309, 2023). "Deep phenotyping data, blood biobank, cardiac stress-MRI test, and identified candidate biomarkers (such as miRNAs, troponin, CRP, etc.) will be used to derive a biomarker specifically for ischemia." (PMID 36902588, 2023). "Inflammatory systemic response was also lower in patients with ischemia: CRP (mean difference, MD −29.01 [−42.61, −15.41], p < 0.001), ESR (MD −5.70 [−9.71, −1.69], p = 0.005), whereas hemoglobin was higher (MD 0.49 [0.19, 0.79], p = 0.001)." (PMID 38130834, 2023).
ischemia (continued). "The survival rate of patients without significant amputation was shown to be negatively impacted by the presence of ischemia, older age, and a higher level of C-reactive protein." (PMID 37762756, 2023). "This is partially at odd with our previous findings showing a correlation between sP2X7R and CRP in a cohort of patients affected by different pathologies (infections, cancer, ischemia and others)." (PMID 37215142, 2023). "C-reactive protein (CRP) is a positive acute phase protein produced in the liver following a cytokine-induced stimulation as a result of ischemia, trauma, or inflammation." (PMID 38293658, 2023). "CRP, as an acute phase protein in inflammatory response, is significantly higher than normal when the body has serious infection, ischemia, and other changes." (PMID 35399851, 2022). "Predictive value of CRP for clinical outcomes in patients with ischemia-related cardiovascular diseases." (PMID 36556477, 2022). "Post hoc analysis of risk factors for visceral ischemia in OA-treated patients only found lower mean CRP value in patients enduring ischemia compared to other patients." (PMID 34112205, 2021). "A large body of data obtained either in rats, porcine models or in vitro in the infarcted myocardium of humans has demonstrated that CRP plays an active role in exacerbating ischemia and reperfusion-induced damage." (PMID 33679775, 2021). "C-reactive protein concentrations also increase substantially during acute ischemia and return to near basal levels during the chronic stable phase after ischemia is resolved." (PMID 33628645, 2021). "The results showed that the level of CRP concentration increased during the ischemia compared to baseline, and the maximum peak was at 15 min after reperfusion and reduced by passing 24 h from reperfusion; and at the same time, it was higher than the baseline." (PMID 34631170, 2021). "The values of CRP between in the simple intestinal obstruction group and the necrosis subgroup as well as between the ischemia subgroup and the necrosis subgroup were also statistically different (P<0.01)." (PMID 34292211, 2021). "Fib and CRP demonstrate good performance in predicting strangulation and are indicative of intestinal necrosis and ischemia." (PMID 34292211, 2021). "CRP is an easily available positive acute-phase protein, which increases as a result of infection, ischemia, and/or trauma." (PMID 32344777, 2020). "Nevertheless, there is paucity of data regarding the role of high sensitivity (hs)-C-reactive protein (CRP) to albumin ratio (CAR) in patients with ischemia on gated single photon emission tomography (SPECT) myocardial perfusion imaging (MPI)." (PMID 33094574, 2020). "Baseline CRP or hs-CRP levels increase with aging, and therefore, both higher levels of CRP and the presence of ischemia in MPI could be the consequences of aging." (PMID 38398769, 2024). "In the literature, many studies focus on different predictive systemic and peritoneal drain biomarkers (inflammatory, microbiological, markers of ischemia) and frequently mention CRP, procalcitonin (PCT), neutrophil-to-lymphocyte ratio, white blood cell count and IL-6." (PMID 38098074, 2023). "As it is known to increase after ischemia, C-reactive protein (CRP) may serve as a surrogate for systemic inflammation and thus be a hallmark of increased tissue vulnerability." (PMID 37360331, 2023). "To prove this hypothesis, we performed myocardial miRNA expression profiling in the ischemia-reperfusion injury rat model with CRP infusion using high-throughput NanoString nCounter technology." (PMID 31063484, 2019). "Both CRP and sP2X7R levels were significantly higher in the infectious disease patients vs. the other three subgroups, with the exception of sP2X7R in the ischemia patients (Mann Whitney test: p = 0.268)." (PMID 31031771, 2019). "In the present study, we hypothesized that serum CRP would change miRNA profiles of damaged myocardium by ischemia-reperfusion injury." (PMID 31063484, 2019).
ischemia (continued). "In an animal experiment, after adnexal ischemia, the plasma CRP level was found to be elevated." (PMID 30533300, 2018). "Immunofluorescence with conformation specific detection of CRP and CD68+ cells in striated human muscle tissue shortly before (pre-ischemia) and after free tissue transfer (post-reperfusion) revealed extensive deposition of neo-epitope expressing CRP in the IRI-challenged tissue." (PMID 29713320, 2018). "High-sensitivity C-reactive protein (hs-CRP) rises with cardiac injury/ischemia." (PMID 21702934, 2011). "During the proliferative stage of ED, inflammation subsided clinically which is also demonstrated by an almost normal level of CRP in the serum of the patients, retinal neovasculation and vitreous hemorrhage have already developed as a consequence of retinal hypoxia and ischemia." (PMID 22025890, 2011). "The excessive levels of CRP we see in the CAD+ arm may be an indication of vascular inflammation and vessel damage not only localized to the affected artery but may also reflect ischemia in other vascular beds associated with HD." (PMID 41342048, 2025). "Moreover, we observed an association between WBC counts, hs-CRP and FFAs levels in incident ACS and higher Gensini score, which implied a possible interaction between FFAs and inflammation processes influenced the severity of ischemia." (PMID 26830193, 2016). "Male sex, elevated SII, and increased C-reactive protein (CRP) and neutrophile-to-lymphocyte ratio (NLR) values were also significantly related to ischemia." (PMID 40506944, 2025). "While biomarkers like CRP are well-known predictors of MACE, their direct link to residual lesion ischemia and plaque instability has been largely unexplored in ACS patients post-revascularization." (PMID 41226718, 2025). "In multivariate analysis, NPS (p < 0.001), SII (p = 0.023), CRP (0.005), and NLR (0.037) values remained independent predictors of ischemia." (PMID 40506944, 2025). "Recently, another index, i.e., the ratio of two inflammatory markers (CRP to albumin; CAR), was investigated for the prediction of ischemia." (PMID 38398769, 2024). "Ischaemia-modified albumhumin (IMA), serum D-dimer (s-DD), heat shock protein-70 (hsp-70), Pentraxin-3 (PTX3), and c-reactive protein (CRP) each showed the most promise, with p-values for the difference between OT and control groups achieving ≤ 0.001." (PMID 39519217, 2024). "The inflammatory cytokines rising in COPD, such as IL-6, C-reactive protein and TNF-α, would also lead to ischemia, which further implies that inflammation can trigger pulmonary hypertension by changing the blood vessels of the pulmonary cycle." (PMID 33108241, 2020). "During ischemia, primary cytokines, such as IL-1 and TNF-α (along with an increase in the concentration of C-reactive protein (CRP)), are released into the bloodstream." (PMID 32751587, 2020). "According to laboratory findings, hs-CRP and CAR were significantly higher in the ischemia group, while the serum albumin was significantly lower in ischemia group (p<0.05 for each)." (PMID 33094574, 2020). "Undoubtedly, postoperative CRP levels can correlate with new problems such as progredient ischemia, fracture, or thrombosis, but the CRP level does not really help whenever these problems are recognized visually." (PMID 40565868, 2025). "Similarly, in our study, CRP, WBC, neutrophils and NLRs among inflammatory markers were higher in the ischemia group." (PMID 40506944, 2025). "The presence of ischemia, older age, and increased C-reactive protein diminished survival in patients without major amputation." (PMID 37510519, 2023). "TMZ reduces the release of proinflammatory mediators from macrophages induced by reactive oxygen species, including C-reactive protein (CRP), tumor necrosis factor-alpha (TNF-α), interleukin 1 (IL-1), and interleukin 8 (IL-8) during both inflammation and ischemia." (PMID 35538296, 2023).
ischemia (continued). "Several studies showed that CRP is strongly associated with the risk of CVD and ischemia in individuals with no history of vascular disease." (PMID 37569355, 2023). "The symptom of ongoing ischemia did not correlate with the presence of fever in our study populace but was found to correlate with CRP levels suggesting a relationship of symptomatology to inflammation." (PMID 31088357, 2019). "In contrast to these prior publications, we want to evaluate the routine CRP controls in the aftermath of acute orthopedic foot SSIs, mostly in the hospitalization setting, without the interference of (chronic) ischemia and other concomitant reasons for non-infectious skin breakdowns." (PMID 40565868, 2025). "However, C-reactive protein is not a specific marker to indicate rejection or infection or ischemia after kidney transplantation." (PMID 26445912, 2015). "We focused on uneventful postoperative courses after the first debridement procedure for an SSI, without new events that might alter the indications for CRP measurement for new complications such as lung embolism, ischemia (especially in the diabetic foot), or nosocomial urinary tract infections." (PMID 40565868, 2025). "The oxidative stress markers yielded contrasting results, with significant differences in CRP and SOD levels between the groups, yet no variance in ischemia‐related indicators." (PMID 41346959, 2025). "However, for those with ischaemia who may also have had urgent surgery, the CRP was no raised." (PMID 31095593, 2019). "We observed in this unique population of women with signs and symptoms of ischemia, non-obstructive CAD and preserved EF at enrollment, IL-6 was the strongest predictor of HF hospitalization in these women compared to hs-CRP and SAA level, especially in the highest quartile (>4.79 pg/mL)." (PMID 28542263, 2017).